TRIM25 (tripartite motif containing 25)
Diseases named in the same sentence as TRIM25 in open-access papers (continued):
Sharing a sentence is not in itself a finding about the gene and the disease.
ovarian carcinoma (7 papers, 2016 to 2025). A malignant neoplasm originating from the surface ovarian epithelium. "Particularly, the HECT domain and the RCC1-like domain-containing protein 5 (HERC5) and estrogen-responsive finger protein (EFP or TRIM25), known as E3 ligase of ISGylation have been shown to be associated with liver, breast prostate, endometrial and ovarian cancers 15-18." (PMID 32132870, 2020). "For example, TRIM25 is overexpressed in ovarian cancer, but is down-regulated in endometrial cancer." (PMID 27793172, 2016). "Among them, only the expression of tripartite‐motif protein 25 (TRIM25) and TRIM56 predicted good survival for ovarian cancer patients." (PMID 39887931, 2025). "We also found increased ISG15 expression and an increased ISGylation profile in HGSOC patient tissues and in tumour and ascites derived from an orthotopic ovarian cancer mouse model along with USP18 and ISGylating enzyme TRIM25." (PMID 38939897, 2024).
endometrial cancer (6 papers, 2016 to 2025). Primary or metastatic malignant neoplasm involving the endometrium (mucous membrane that lines the endometrial cavity). "TRIM25 recognizes 14-3-3σ and promotes its degradation to reduce its activity in breast and endometrial cancer, promoting cancer cell survival and proliferation." (PMID 40431746, 2025). "Overexpression of SNORD15B also upregulated TRIM25 protein in the endometrial cancer cells in vitro and in the tumor xenograft." (PMID 36199797, 2022). "Taken together, we can surmise that SNORD15B upregulates both TRIM25 expression and activity in endometrial cancer cells." (PMID 36199797, 2022).
glioblastoma (6 papers, 2024 to 2026). The most malignant astrocytic tumor (WHO grade IV). "One of best-characterized examples supporting the strong pathological impact of TRIM25 is glioblastoma." (PMID 39851496, 2025). "TRIM25 expression is frequently upregulated in glioblastoma, correlating with higher tumor grades and resistance to TMZ." (PMID 41511341, 2025). "Our study demonstrates that TRIM25 promotes glioblastoma cell growth and invasion by regulating the PRMT1/c-MYC pathway through mediation of the splicing factor NONO." (PMID 38303029, 2024). "The results showed that the TRIM25 expression level was significantly higher in glioblastoma (GBM, n = 156) than in NBT (n = 4)." (PMID 38303029, 2024). "We observed upregulation of TRIM25 in GBM, correlating with enhanced glioblastoma cell growth and invasion, both in vitro and in vivo." (PMID 38303029, 2024). "Mechanistically, TRIM25 inhibits oxidative stress and ferroptotic cell death during TMZ treatment by promoting the nuclear import of Nrf2 through Keap1 ubiquitination, highlighting its role in glioblastoma chemoresistance and its promise as a therapeutic target." (PMID 41511341, 2025).
colon carcinoma (5 papers, 2019 to 2024). "Together, these data suggest that TRIM25 represents a novel caspase-7 mRNA-binding protein, which, in concert with RNA-bound hnRNPH1, promotes the constitutive decay of caspase-7 mRNA in colon carcinoma cells." (PMID 36611995, 2023). "The analysis of the gene-specific changes in the proteome of the human colon carcinoma cell line RKO by mass spectrometry identified a total of 226 putative TRIM25 target proteins significantly altered in TRIM25 downregulated cells." (PMID 36611995, 2023). "In this study, we report caspase-7 as a novel target of the E3 ligase TRIM25 in different human colon carcinoma cell lines and in HEK293 cells." (PMID 36611995, 2023). "Together, these data suggest that TRIM25 contributes to the resistance of colon carcinoma cells towards drug-induced cell death post-transcriptionally through suppression of caspase-7 expression." (PMID 36611995, 2023). "Previously, we described the fact that the constitutive binding of the E3 ligase TRIM25 to caspase-2 mRNA represses caspase-2 translation in human colon cancer cells, thus leading to an impaired sensitivity towards drug-induced apoptosis." (PMID 36611995, 2023). "TRIM25 binds to caspase-2 mRNA and downregulates caspase-2 protein levels to mediate drug insensitivity in colon carcinoma cells." (PMID 36012594, 2022). "In colon cancer cells, TRIM25 expression is increased upon ER stress and upregulated TRIM25 reduces Keap1, an inhibitor of Nrf2, by its ubiquitination and degradation." (PMID 36552825, 2022). "Monitoring of the time-dependent effectiveness of TRIM25 knockdown (siTRIM25) revealed a strong and stable decrease in TRIM25 protein expression in both colon carcinoma cell lines tested, whereas transfection with a scrambled siRNA (siCtrl)." (PMID 31842382, 2019). "In this study, we reported on the identification of TRIM25 as a novel potential regulator of caspase-2 translation in human colon carcinoma cells." (PMID 31842382, 2019). "Together, these data demonstrate that transient siRNA-dependent depletion of TRIM25 via increased caspase-2 translation sensitizes colon carcinoma cells to the intrinsic apoptotic pathway." (PMID 31842382, 2019). "In the present study, we unveil a novel mRNA modulatory function of TRIM25, which is critically involved in the negative regulation of caspase-2 in different colon carcinoma cell lines." (PMID 31842382, 2019). "Using RNA affinity chromatography, we identified the tripartite motif-containing protein 25 (TRIM25) as a bona fide caspase-2 mRNA-binding protein in colon carcinoma cells." (PMID 31842382, 2019). "Together, our study identified the E3 ligase TRIM25 as a novel caspase-2 RNA-binding protein in colon carcinoma cells, which negatively affects protein expression of caspase-2." (PMID 31842382, 2019). "Together, these results demonstrate that silencing of TRIM25 expression sensitizes colon carcinoma cells to chemotherapeutic drug-induced intrinsic apoptosis by a mechanism that critically depends on caspase-2." (PMID 31842382, 2019). "To test whether in colon carcinoma cells TRIM25 is also a target of constitutive ubiquitination, we used ubiquitination affinity beads, which allow the capturing of ubiquitinated proteins with high affinity from whole cell lysates." (PMID 36611995, 2023). "In the present study, we unveil the destabilization of caspase-7 mRNA as a novel mRNA modulatory function by TRIM25, which may functionally contribute to the pathological downregulation of caspase-7 observed in colon carcinoma." (PMID 36611995, 2023). "Inspired by these data, we questioned whether members of the hnRNP family would also interact with TRIM25 in colon carcinoma cells." (PMID 36611995, 2023).
colon carcinoma (continued). "The negative posttranscriptional gene regulation of caspase-7 by TRIM25 found here may at least partially account for the impaired caspase-7 expression in colon cancer." (PMID 36611995, 2023). "The key finding of our study is that inhibition of caspase-2 by TRIM25 constitutes a so far unrecognized pathway, which may be relevant for the resistance of human colon carcinoma cells to chemotherapy-induced apoptosis." (PMID 31842382, 2019). "Together, these data suggest that the increased sensitivity of colon carcinoma cells to doxorubicin-induced apoptosis by TRIM25 silencing results from convergent activation of mitochondrial apoptosis (via silencing of TRIM25) and drug-mediated activation of receptor-triggered apoptosis." (PMID 31842382, 2019). "Interestingly, the upregulation of caspase-2 upon TRIM25 silencing alone is unable to trigger apoptosis in colon carcinoma cells but requires an additional apoptosis-inducible stimulus, such as doxorubicin." (PMID 31842382, 2019). "Downregulation of TRIM25 leads to an increase in USP25 levels, which in turn induces chemoresistance in colon cancer cells." (PMID 38803048, 2024). "We then used the Ualcan dataset to select four candidate E3 ligases (TRIM25, HECTD3, NEDD4L, WWP2) whose mRNA levels were lower in colon cancer tissue samples compared to normal colon tissues." (PMID 38803048, 2024). "Conversely, knockdown TRIM25 rendered colon cancer cells resistant to 5‐Fu treatment in ctrl cells but not USP25‐depleted SW480 cells." (PMID 38803048, 2024). "We also observed a negative correlation between USP25 and TRIM25 protein expression in the colon tumor samples." (PMID 38803048, 2024). "Furthermore, the increase in caspase-2 upon TRIM25 knockdown was only observed on the protein level but not on the mRNA level, independent of the colon carcinoma cell line that was assessed." (PMID 31842382, 2019).
bladder cancer (3 papers, 2022 to 2025). "Fourteen TRIM family proteins were associated with bladder cancer (tumor-promoting: TRIM9, TRIM25, TRIM26, TRIM28, TRIM29, TRIM59, TRIM65, and TRIM66; tumor-suppressive: TRIM19 and TRIM38)." (PMID 40723250, 2025). "For instance, TRIM25-mediated ubiquitination accelerates RBPJ degradation via proteasome in bladder cancer validated by immunoprecipitation without further studying the binding residues." (PMID 40723303, 2025). "Similarly, in bladder cancer cells, overexpressed RITA1 induced degradation of RBPJ by recruiting the E3 ligase TRIM25." (PMID 36293193, 2022).
severe acute respiratory syndrome (3 papers, 2019 to 2025). A viral respiratory infection caused by the SARS coronavirus. "Severe acute respiratory syndrome nucleocapsid inhibited TRIM25-mediated RIG-I ubiquitination, causing the inhibition of IFN production." (PMID 31849979, 2019). "Interestingly, TRIM25 itself is target of severe acute respiratory syndrome Coronavirus-2 (SARS-CoV-2), mainly through the inhibition of TRIM25–RIG-1 interaction." (PMID 39851496, 2025). "Severe acute respiratory syndromes (SARS) and middle east respiratory syndrome (MERS) coronavirus N protein could counteract with human TRIM25 to suppress RIG-I activation." (PMID 31143181, 2019).
acute myeloid leukemia (2 papers, 2021 to 2025). Acute myeloid leukemia (AML) is a group of neoplasms arising from precursor cells committed to the myeloid cell-line differentiation. "In acute myeloid leukemia (AML), TRIM25 can promote tumor cell proliferation and migration, and its expression is negatively regulated by miRNA-137." (PMID 40431746, 2025).
cholangiocarcinoma (2 papers, 2024 to 2025). A carcinoma that arises from the intrahepatic biliary tree (intrahepatic cholangiocarcinoma) or from the junction, or adjacent to the junction, of the right and left hepatic ducts (hilar cholangiocarcinoma). "A previous study on cholangiocarcinoma (CCA) identified TRIM25 as a negative regulator of AZGP1 and suggested that pathologically reduced AZGP1 may result from increased TRIM25 levels, since patients suffering from CCA were nearly deficient in AZGP1, but showed a high amount of TRIM25." (PMID 39851496, 2025).
COVID-19 (2 papers, 2021 to 2022). A disease caused by infection with severe acute respiratory syndrome coronavirus 2. "Consistent with prior analysis however, TRIM25 remains elevated in both severe ICU COVID-19 and ventilation-associated cases." (PMID 33633121, 2021). "With non-severe (non-ICU) COVID-19, there was increased expression of the viral entry gene (CTSL (p < 0.05)) and increased antiviral response genes (MX1 (p < 0.0001), SAMHD1 (p < 0.0001), TRIM25 (p < 0.01), IFITM3 (ns))." (PMID 33633121, 2021). "For patients with COVID-19 who were not admitted to ICU, there was a statistically significant relationship between viral defense genes and CTSL expression, the four predictors (MX1, TRIM25 SAMHD1 and IFITM3) accounted for 65.56% of the variance (adjusted R2 = 0.656, p-value = 8.796–11)." (PMID 33633121, 2021).
HIV-1 infection (2 papers, 2012 to 2019). The type species of lentivirus and the etiologic agent of acquired immunodeficiency syndrome (AIDS). "The rhesus monkey TRIM5α blocks HIV-1 infection by recognizing HIV-1 core via PRYSPRY domain, and the SPRY domain of TRIM25 mediates its association with RIG-I." (PMID 23056470, 2012). "Compared to our findings, IRF7, TRIM25, and MX2 were the ‘common ISGs’ that exhibited anti-HIV-1 effects in MT-4 cells and were upregulated by HIV-1 infection." (PMID 30915053, 2019). "Moreover, certain ‘common ISGs’ that were upregulated by HIV-1 infection (IRF7, TRIM25, MYD88, MX2, LGALS9, and SP100) exhibited a strong anti-HIV-1 effect in THP-1 cells." (PMID 30915053, 2019).
nasopharyngeal carcinoma (2 papers, 2024 to 2025). A carcinoma arising from the nasopharyngeal epithelium. "Mechanistically, a recent publication has described radiosensitivity in nasopharyngeal carcinoma mediated by the deubiquitinase USP44 via stabilization of the E3 ubiquitin ligase TRIM25 and subsequent TRIM25-mediated Ku80 degradation." (PMID 39478631, 2024). "In a clear contrast to the so-far described scenarios in which TRIM25 has been commonly shown as an oncogenic protein which can essentially contribute to chemoresistance of many human cancers, data from nasopharyngeal carcinoma (NPC) clearly imply an opposite role of this particular TRIM member." (PMID 39851496, 2025).
ovarian tumor (2 papers, 2016 to 2024). "It is reported that ovarian tumor (OTU) domains of CCHFV and HAZV interfere with host innate immune system via the ubiquitin protease activity and HAZV N protein interferes with the binding of TRIM25 to RIG-I and subsequent activation of RIG-I." (PMID 39348382, 2024).
triple-negative breast carcinoma (2 papers, 2024 to 2025). An invasive breast carcinoma which is negative for expression of estrogen receptor (ER), progesterone receptor (PR), and human epidermal growth factor receptor 2 (HER2). "In a previous study, Zheng and colleagues (2024) unraveled a novel mechanism by which TRIM25 promotes autophagy-triggered resistance of triple-negative breast cancer to taxanes." (PMID 39851496, 2025).
ZIKV infection (2 papers, 2022 to 2023). "To further analyze the role of TRIM25 during ZIKV infection, we utilized dicer-substrate siRNA (DsiRNA) targeting TRIM25 (siTRIM25) or a non-targeting DsiRNA control (siControl)." (PMID 35632712, 2022). "These experiments show that levels of TRIM25 protein were not depleted during ZIKV infection." (PMID 35632712, 2022).
acute promyelocytic leukemia (1 paper, 2022). An aggressive form of acute myeloid leukemia (AML), characterized by arrest of leukocyte differentiation at the promyelocyte stage, due to a specific chromosomal translocation t(15;17) in myeloid cells. "It has been reported that RIG-I binds to Trim25 mRNA in acute promyelocytic leukemia (APL) cells following all-trans RA (ATRA) treatment, which upregulates TRIM25 expression and induces ISGylation, contributing to myeloid differentiation and maturation." (PMID 36319753, 2022).
Autoimmunity (1 paper, 2023). The occurrence of an immune reaction against the organism's own cells or tissues. "Given the potential link of ZC3HAV1 as well as TRIM25 with autoimmunity, we presume that genetic polymorphisms in ZC3HAV1 and TRIM25 might confer susceptibility to VKH disease." (PMID 37221558, 2023). "Several studies also indicated that TRIM25 is involved in the development of autoimmune disorders and inflammation." (PMID 37221558, 2023).
breast tumor (1 paper, 2020). "In addition, the expression level of TRIM25 and Nrf2 were also inversely correlated to Keap1 in breast tumor tissues from TCGA database." (PMID 31953436, 2020).
cardiomyopathy (1 paper, 2022). A disease of the heart muscle or myocardium proper. "Given that TRIM25 functions as a feedback mechanism that responds to endoplasmic reticulum (ER) stress, and that the dysregulation of ER homeostasis in the heart is implicated in cardiovascular disease, including DOX cardiomyopathy, we further examined the ER stress-related protein in heart tissues." (PMID 35871160, 2022).
colorectal adenocarcinoma (1 paper, 2021). The most common type of colorectal carcinoma. "Further co-immunoprecipitation experiments in human colorectal adenocarcinoma HT-29 cells revealed that endogenous RIP3 interacted with TRIM25." (PMID 33953350, 2021).
Cop (1 paper, 2025). "To further examine whether VACV-Cop infection of HeLa cells had any consequence on the TRIM25 protein, we performed Western blotting experiments." (PMID 40719442, 2025). "Therefore, we examined whether TRIM25 localization was impacted by VACV-Cop infection." (PMID 40719442, 2025).
dementia (1 paper, 2024). Loss of intellectual abilities interfering with an individual's social and occupational functions. "Further, RNA-seq data suggests low abundance of HERC5 and TRIM25 in brain samples analysed from individuals with aging, dementia or with traumatic brain injury, when compared with healthy subjects." (PMID 38431611, 2024).
dermatomyositis (1 paper, 2023). Dermatomyositis (DM) is a type of idiopathic inflammatory myopathy characterized by evocative skin lesions and symmetrical proximal muscle weakness. "A previous study has demonstrated upregulation of TRIM25 in muscle samples from dermatomyositis patients." (PMID 37221558, 2023).
disc degeneration (1 paper, 2026). "In a rat model of compression-induced IVDD, restoring PAR homeostasis by targeting the TRIM25-PARG axis significantly attenuated disc degeneration, suggesting the therapeutic potential of targeting this pathway in IVDD." (PMID 41700742, 2026).
endometriosis (1 paper, 2023). The growth of functional endometrial tissue in anatomic sites outside the uterine body. "Seven genes, namely, APPL1, CSNK2A1, ERG, KDM4A, SMARCC1, SUZ12 and TRIM25, were selected to establish the diagnostic model for endometriosis, and a nomogram was constructed based on them." (PMID 36860677, 2023).
enterovirus infection (1 paper, 2024). "TRIM25 mediates the RIG-I ubiquitination and restores its expression and IFN-β production, indicating that TRIM25 can abolish enterovirus infection." (PMID 38596371, 2024).
Ewing sarcoma (1 paper, 2021). A small round cell tumor that lacks morphologic, immunohistochemical, and electron microscopic evidence of neuroectodermal differentiation. "Our analysis identified TRIM25, APP, ELAV1, RNF4, and HNRNPL as ideal mRNA targets for Ewing sarcoma therapy." (PMID 34662337, 2021).